MIR520A (microRNA 520a)
Synonyms: hsa-mir-520a; MIRN520A
Gene: MicroRNA gene on chromosome 19 (53,690,881 to 53,690,965, forward strand). Ensembl gene ENSG00000207594.
Gene Ontology:
Biological process: miRNA-mediated post-transcriptional gene silencing